CD80 (CD80 molecule)
Diseases named in the same sentence as CD80 in open-access papers (continued):
Sharing a sentence is not in itself a finding about the gene and the disease.
tumor (1,343 papers, 1998 to 2026). "Decreased anti-tumor immune responses in the tumor microenvironment have been associated with the CTLA-4/CD80,CD86 axis between immune cells and tumoral cells (Derakhshani, Hashemzadeh, Asadzadeh, and Shadbad 2021)." (PMID 39905036, 2025). "Tumor co-culture induced further enhancement of M1-associated markers including CD80/CD86, MHC-II and IL-1β/IL-6/TNF-α/IL-12/IFN-γ, while suppressing M2 markers CD163/CD206, indicating tumor-triggered M1 polarization." (PMID 41388305, 2025). "We found that treatment with NOC47‐Ce6+Laser significantly upregulated various M1‐associated markers in the tumor tissues, including CD80, CD86, and IL family cytokines." (PMID 40287972, 2025). "Several studies have observed the activation of CD8+ and CD4+ T cells when exposed to DCs exosomes associated with the induction of an anti-tumor immune response in vivo through exosomal CD80 and endogenous IL-2." (PMID 40141358, 2025). "Another possible explanation is that PD‐L1 binds two receptors, PD‐1 and B7.1 (CD80), and B7.1 is a key co‐stimulatory molecule on tumor‐associated dendritic cells (DC) that enhances T‐cell initiation through B7.1/CD28 interaction." (PMID 39500635, 2024). "Compared to the other myeloid-associated antigens used in this study, tumor cells were CD80+ in a higher proportion of dogs with AML." (PMID 39224452, 2024). "It is also possible that CD80 and other myeloid-associated antigen expression on residual normal monocytes or neutrophils contributed to the percentage of positive cells in the tumor cell gate." (PMID 39224452, 2024). "It was found that introducing mutations in the interaction site on PD-L1 or on CD80 significantly suppressed the anti-tumor immune response in mice." (PMID 39575257, 2024). "Given the fact that PD-1/CD80+ aT-sEVs impaired anti-PD-1 blockade therapy in vivo, we then investigated the association between PD-1/CD80+ aT-sEVs and tumour-infiltrating CD8 T lymphocytes (TILs), which are an important factor of the antitumour immunity." (PMID 38719909, 2024). "A higher proportion of tumor cells in dogs with AML were labeled with the anti-CD80 antibody vs antibodies against other myeloid-associated antigens, including CD4 (36%, p = 0.003), CD11b (44%), CD11c (46%), CD14 (38%, p = 0.006) and CD18 (59%, clone YFC118)." (PMID 39224452, 2024). "Tumor regression caused by cps therapy is associated with high‐level expression of T‐cell receptor costimulatory molecules CD80 and CD86 and IL‐12 and IFN‐γ, which are crucial for activating antitumor T‐cell immunity." (PMID 38109851, 2024). "Taken together, these data clearly demonstrated that the chronic HS diet resulted in TGFβ-mediated cell surface expression of CD80 in TISCs, which is associated with immune exhaustion and tumor progression." (PMID 38891044, 2024). "They found that PE promoted the expression of MHC II and co-stimulatory molecules CD86 and CD80 on tumor-associated dendritic cell (TADCs), induced the production of IL-12 by TADCs, and enhanced the proliferation of both CD8+ T and CD4+ T cells." (PMID 39364399, 2024). "Some studies have also shown that CD80-Fc can enhance T cell immune responses to a variety of tumor-associated antigens including Survivin and HPV, showing its potential as a universal adjuvant for tumor vaccines." (PMID 39575257, 2024). "The use of ICIs to block PD-1/PD-L1 and CTLA-4/CD80/86 signaling pathways enhances the efficient immune responses against cancer cells, revitalizing tumor antigen recognition and causing tumor death." (PMID 39409094, 2024). "One of the first clues of the existence of the cis PDL1:CD80 interaction came from the finding that CD80 coexpression renders PDL1-positive tumor cells more susceptible to T cell–mediated killing." (PMID 37339682, 2023).
tumor (continued). "The interactions between the ITIM containing receptors and their ligands including but not limited to PD-1/PD-L1 and CTLA-4/CD80/86, are known to be involved in tumor development as well as loss of immune regulation." (PMID 36960400, 2023). "CD80 has been mainly used as an immunoadjuvant molecule in tumor or pathogenic microorganism vaccines to excite antigen‐specific T cells by transfection or co‐expression with antigens in vector cells." (PMID 37476068, 2023). "All tumors treated with macrophage polarization modulators showed the presence of tumor-associated macrophages with increased M1-phenotype markers (CD80+ F4/80+ )." (PMID 35468901, 2022). "CK2 inhibitor can downregulate PD-L1 expression and enhance the level of CD80 on tumor-associated DCs and promote the CD80/CD28 interaction to enhance T-cell priming to inhibit tumor progression." (PMID 36530985, 2022). "Previous studies have showed that the CD80 expression is lower in several cancer cells, and the loss of CD80 alone promotes their ability to escape the attack from the immune system and imparts energy and apoptosis in tumor-infiltrating T cells." (PMID 35814211, 2022). "To further dissect changes in leukocyte populations, we next analyzed tumor-associated macrophages (TAMs) and identified significantly decreased CD80+ M1-polarized macrophages from tumor tissues in IP6K1 KO mice." (PMID 35308129, 2022). "Conversely, on transfecting tumor cells with CD80, the tumor cell is found to be more susceptible to the lysis by T cells ex vivo." (PMID 36387279, 2022). "Tumour-associated macrophages (TAM) were shown to drive this ICB resistance through PD-L1/CD80-mediated CD4+ T-cell suppression and Treg expansion." (PMID 35454848, 2022). "Tumor‐associated macrophages protect cancer cells through eliminating the anti‐tumor T cells by overexpressing PD‐L1, PD‐L2, CD80, and Siglec‐15." (PMID 34898004, 2022). "CD80 deactivation in these cells was associated with a “hotter” microenvironment, decreased tumor growth, and enhanced sensitivity to CTLA-4 blockade." (PMID 33923750, 2021). "PD-L1-blocking antibodies prevent CD80/PD-L1 interaction on tumor-associated dendritic cells (DCs) and promote the CD80-mediated anti-tumor immune response." (PMID 33923750, 2021). "On the contrary, overexpression of CD80 promotes T cell activation and tumor rejection, and a CD80 deficiency also increases the immunogenicity of tumor cells." (PMID 33923750, 2021). "Intraperitoneal injection of epacadostat caused a significant increase in tumor volume, tumor weight, while it concomitantly inhibited CD80 expression of macrophages in tumor tissues." (PMID 33390854, 2021). "In this study, we generated CD80/CD86-targeted CAR T cells to destroy CD80/CD86-associated tumor cells in culture and in the tumor xenograft mouse models." (PMID 33868277, 2021). "Tumor-associated macrophages in Frount-deficient mice also displayed lower expression of the activation markers CD80, CD86 and MHC class II, as well as M2 macrophage marker CD206, compared to those in control mice." (PMID 32001710, 2020). "We further explored the correlation between PINK1 expression and representative immune markers in LIHC and LUSC, and PINK1 expression was more strongly correlated with tumor-associated macrophage markers such as HLA-G, CD80, and CD86 in LUSC than in LIHC." (PMID 33244455, 2020). "CD80 has been linked to promoting anti-tumor immune responses in multiple mouse models of cancer, and exogenous administration of recombinant CD80 protein can promote anti-tumor immunity." (PMID 31959281, 2020). "CD80-Fc enhanced T cell responses to multiple tumor-associated antigens including Survivin and HPV, indicating its potential as a universal adjuvant for cancer vaccines." (PMID 32161596, 2020).
tumor (continued). "In vitro functional studies using THP-1 derived macrophages revealed CD38 expression to be associated with the M1 state, characterized by CD80 expression and secretion of TNFα and IL-6, all of which contribute to the anti-tumor immune response." (PMID 31552039, 2019). "Upregulation of CD80 on tumor cells has been shown to render them more susceptible to lysis by T cells." (PMID 31112530, 2019). "We previously reported that systemic administration of rat anti-tumour IgE was associated with recruitment of CD80+ macrophages into syngeneic tumours of immunocompetent rats." (PMID 30956175, 2019). "We observed that monocytes cultured with either IL32β or IL32γ express both CD68 and CD80, markers associated with M1 proinflammatory macrophages thought to play an anti-tumor role." (PMID 30953519, 2019). "In conclusion, mPGES-1 inhibition elevates CD80 expression by tumor-associated phagocytes to restrict tumor growth." (PMID 25871398, 2015). "Tumor cells from miR-146a-deficient mice showed lower expression of memory B-cell/activation related antigen, CD80, but similar expression of CD44." (PMID 25906746, 2015). "In this model, tumor killing required CD80 expression by tumor-associated phagocytes to trigger cytotoxic T cell activation." (PMID 25871398, 2015). "This suggested PGE2 as a prostanoid responsible for modulating CD80 expression on tumor-associated phagocytes." (PMID 25871398, 2015). "Taken together, signaling via the EP2/cAMP-pathway counteracted LPS/C3-induced CD80 expression in tumor-associated human phagocytes and reduced the expression of the anti-inflammatory macrophage marker CD206." (PMID 25871398, 2015). "Previous study paid excessive attention to the function of tumor-associated B7-H1 which take effect as a ligand for PD-1 or CD80, but neglected the effect of tumor-associated B7-H1 itself on tumor cell." (PMID 24124529, 2013). "This timeline of Treg expansion by RT immediately follows our observed CD80/86 upregulation by RT, therefore we hypothesized that CD80 upregulation by RT suppresses anti-tumor immunity by causing Treg expansion." (PMID 41417245, 2025). "Overall, we can conclude that while inducing anti-tumour-associated Cd40 and Cd80 and reducing pro-tumorigenic VISTA, SFV also upregulated PD-L1 which could interfere with the therapeutic effect." (PMID 40547518, 2025). "However, simultaneous treatment of mice with PD-L1 and CTLA-4 antibodies allows for restored expression of CD80 on tumor-associated DCs, leading to increased CD28 costimulation, downstream T cell responses, and reduced overall tumor burden." (PMID 39879305, 2025). "Next, we investigated the association between aT-sEV PD-1/CD80 and tumour cell PD-L1 expression." (PMID 38719909, 2024). "PD-L1 expression in tumor cells and lymphocytes was associated with a poor prognosis in a study evaluating the expression of CD80, CD86, and PD-L1 in both the tumor and lymphocytes in renal cell tumor cases in the literature, whereas CD80 and CD86 expressions were not correlated with the prognosis." (PMID 37614091, 2024). "In contrast, tumor samples with low expression of CD80 were enriched in genes associated with ribosomal large subunit biogenesis, oxidoreductase activity acting on NAD(P)H quinone or similar compound as an acceptor, glutathione metabolism, glycolysis, and gluconeogenesis." (PMID 36892747, 2023). "MC-C tumor immunogenicity was associated with the capacity of MC-C tumor lysate to promote the maturation of DC as evaluated by the up-regulation of cell surface receptors CD80, CD86 and MHC II as well as production of the inflammatory cytokines TNF-α and IL-12p70." (PMID 35922755, 2022). "Hyperthermia stimulates the release of tumor‐associated antigens.Hyperthermia significantly increases the proportion of mature DC subtypes (CD11c+, CD80+, CD86+).Hyperthermia increases the CD8+T number in TME.Hyperthermia increases the expression of IFN‐γ and TNF‐α." (PMID 35908281, 2022).
tumor (continued). "It has been reported that PD-L1 expression on macrophages promotes tumor resistance to anti-PD-1 antibody by interacting with CD80 expressed on T cells and inducing their differentiation into regulatory T cells, thereby causing tumor resistance to anti-PD-1 antibody." (PMID 35990664, 2022). "Studies have shown that NRTUA invasion can convert tumor-associated CD11c+ DCs into an immunostimulatory phenotype, thereby upregulating the expression of IL-12, major histocompatibility antigen I, and T-cell receptor costimulatory molecules CD80 and CD86." (PMID 36118042, 2022). "Current findings suggest that the various combinations of treatments with produced anti-PD-1, CD80-Fc, and 4-1BBL-Fc proteins reduce inhibitory signals while increasing activatory signals, potentially lowering the risk of tumor resistance and improving treatment efficacy." (PMID 36480493, 2022). "As a stable ROS, H2O2 could significantly re‐model tumor‐supportive TAMs to anti‐tumor CD80+CD86+ M1 phenotype via down‐regulating M2‐associated CD206 marker and up‐regulating M1‐assoiated‐CD86, CD80, and MHCII markers." (PMID 37323705, 2022). "Similarly, higher expression of GZMA, STING and fibronectin and lower levels of CD80 were associated with response within tumour compartments." (PMID 35083152, 2021). "Interestingly, higher proportions of tumor‐infiltrating CD40+ or CD86+ pDCs were linked to longer PFS, whereas higher proportions of tumor‐infiltrating CD80+ cDC2s or pDCs foresaw worse clinical outcome as it was linked with shorter PFS." (PMID 33282290, 2020). "Interestingly, higher expression of CD40 and CD80 on cultured tumor‐infiltrating cDC2s and pDCs, respectively, was associated with a worse clinical outcome as they were linked with shorter PFS." (PMID 33282290, 2020). "In addition, PINK1 expression was more strongly correlated with tumor-associated macrophage markers, such as HLA-G, CD80, and CD86, in LUSC than in LIHC." (PMID 33244455, 2020). "Moreover, high expressions of CD80 or CD86 by tumor‐infiltrating pDCs after TLR stimulation were linked with a worse clinical outcome." (PMID 33282290, 2020). "Indeed, within stage III tumors, higher CD68 infiltration in the intra-tumoral regions is associated with decreased overall survival, and a higher CD80/CD163 ratio at the tumor invasive front correlates with a favorable outcome." (PMID 32962159, 2020). "Notably, in a recent study, the activation of MSP-RON in tumor-associated macrophages significantly increased the expression of CD80 and PD-L1, and the combination of anti-RON and anti-CTLA therapy significantly inhibited tumor growth in mice." (PMID 33117355, 2020). "Subsequent studies have demonstrated that CTLA-4 is a molecular component expressed on certain tumor cell lines at various degrees of intensity and can cause apoptosis of CTLA-4-expressing tumor cells after interaction with soluble CD80 or CD86 recombinant ligands." (PMID 29672601, 2018). "We have previously shown that the invasion of ID8DV tumor associated immune suppressed CD11c+ antigen presenting cells by uracil auxotrophs triggered the expression of the T-cell receptor costimulatory molecules CD80 and CD86." (PMID 27447180, 2016). "Regression of CD80+ tumors following this immunotherapy regimen was abrogated in IFNγ deficient mice, and 50% of mice who had complete regression of CD80+ tumors rejected tumor transplantation upon re-challenge, firmly establishing an immune mechanism." (PMID 26690220, 2015). "Cxb further increased CD80 expression in LPS-challenged tumor-associated phagocytes." (PMID 25871398, 2015). "At CD80 rs13071247, an association was observed such that heterozygotes and minor allele homozygotes (AC and CC genotypes) had slightly increased tumor expression (median fold change = 1.04 on the raw scale, 0.06 on the log2 scale) than cases with AA genotype (p = 0.006)." (PMID 23382860, 2013). "Additionally, CD80 expression was strongly associated with tumour diagnosis." (PMID 40725864, 2025).
tumor (continued). "Interestingly, concurrent loss of CD80/CD86 expression is found in CD58-deficient tumor cells." (PMID 39349829, 2024). "We therefore hypothesized that CD80 was associated with tumor purity." (PMID 36892747, 2023). "Our data demonstrated that CD80 modulated tumor-cell stemness and malignant phenotype while restraining antitumor T cell immunity." (PMID 41677629, 2026). "Detailed mechanistic studies indicated that CL-387785 targets TRADD, recruiting RIPK1 to induce necroptosis in tumor cells, with subsequent nuclear translocation of NF-κB, which regulates CD80 transcription." (PMID 41694588, 2026). "Functionally, CD80 knockdown attenuated tumor-sphere-forming capacity and reduced the migration and invasion of tumor cells, whereas CD80 overexpression potentiated these pro-tumorigenic activities." (PMID 41677629, 2026). "In conclusion, our findings indicate that CL-387785 induces necroptosis in tumor cells via the TRADD/RIPK1/NF-κB/CD80 signaling pathway, thereby sensitizing tumors to anti-PD-1 therapy." (PMID 41694588, 2026). "Mice bearing MTCQ1 tumors were treated with 6 fractions at 2 Gy EBRT and tumor growth and the profile of CD8a+ T cells, CD80+ M1 macrophages, and CD206+ M2 macrophages was investigated." (PMID 41141655, 2026). "Further in vivo and in vitro experiments revealed that CL-387785 enhances tumor cell killing by immune cells by inducing CD80 expression on the tumor cell surface, thereby increasing CD8+ T lymphocyte function." (PMID 41694588, 2026). "In preclinical HNSCC models, inhibition of CD80 significantly decreased tumor burden, accumulated CD8+ T cells, and increased the production of cytotoxic effector molecules." (PMID 41677629, 2026). "Here we identify syntaxin 11 as a key regulator that enhances the expression of MHC I and co-stimulatory molecules CD80/CD86 on tumour cell membranes, enabling cancer cells to acquire dendritic-cell-like features." (PMID 41612046, 2026). "During tumor elimination, the interaction of CD80 and CD86 on antigen-presenting cells with CD28 on T cells regulates T-cell activation, thereby initiating T-cell proliferation." (PMID 40343258, 2025). "Flow cytometry results demonstrated that compared to the oe‐NC group, the oe‐NC+M2pep‐Cs NPs/Plerixafor group showed a significant increase in the M1 TAM marker CD80 in mouse tumor tissues, whereas the oe‐CXCR4 group showed a marked decrease." (PMID 40536774, 2025). "The AMPK pathway counteracts mTOR signaling, with AMPK activation in tumor-associated DCs typically inducing tolerogenic properties characterized by improved mitochondrial function, increased FAO and OXPHOS, and diminished CD80/CD86 expression." (PMID 40924040, 2025). "Durvalumab is human IgG monoclonal antibody that binds to PD‐L1 and CD80, and allowing T cells to recognize and kills tumor cells." (PMID 40014265, 2025). "Blockade of PD-1 or CD80 not only impairs T cell migration, but also promotes tumor immune infiltration and tumor control in in vivo models." (PMID 41050676, 2025). "We and others have observed type I IFN expression increased in the tumor environment following radiation at the same timeline as CD80 induction." (PMID 41417245, 2025). "Of note, a heatmap based on GSEA showed several tumor-associated immune checkpoints, such as H2-Ab1, CD86, CD80, and CD276, CD274 (Pdl1), were downregulated upon Prmt3 deletion." (PMID 40050608, 2025). "CD80 is a co-stimulatory molecule that can either activate anti-tumor T-cells or deliver inhibitory signals." (PMID 41194922, 2025). "Upon binding to CD80 (B7-1) or CD86 (B7-2) on antigen-presenting cells or tumor cells, it functions as an inhibitory switch." (PMID 40677703, 2025). "Evidence indicates that ICIs enhance anti-tumor immunity by modulating the PD-1/PD-L1 and CTLA-4/CD80/86 pathways, strengthening tumor antigen recognition and ultimately inducing tumor cell death." (PMID 41244814, 2025).